CD4 (CD4 molecule)
Diseases named in the same sentence as CD4 in open-access papers (continued):
Sharing a sentence is not in itself a finding about the gene and the disease.
Granuloma (continued). "Unlike many of the NHP studies mentioned, peripheral CD4+ T-cell depletion correlated with granulomas that contained fewer CD4+ and CD8+ T cells, less IFNγ production, more neutrophils, more IL-10, and increased Mtb numbers." (PMID 36405707, 2022). "Further analysis of the restoration of CD4+ and CD8+ T cells in granulomas of the 2 treatment groups demonstrated a significantly higher (P < 0.0001) restoration of CD4+ T cells and a lower percentage of CD8+ T cells in the cART/2-week compared with the cART/4-week group." (PMID 34855621, 2022). "IFN-γ was increased to a large extent in perivascular and intravascular locations of perivascular granulomas in egg-treated HIV mice, with CD4+ and γδ T cells and, to a lesser extent, myeloid cells (likely macrophages according to their morphology), being the main cellular sources." (PMID 35954255, 2022). "Lastly, we assess whether increased SIV replication influenced the immunological phenotype of total CD4+ and CD8+ T cells in lung tissue, thoracic lymph nodes (LN), and affected lung and LN granulomas." (PMID 35467372, 2022). "Immunohistochemistry of the lung granulomas of huNRG and huDRAG-A2 mice following intranasal infection with the H37Rv strain of Mtb revealed that both human CD4+ T cells and CD68+ macrophages were involved in the formation of granulomas and the containment of the mycobacterium." (PMID 36146734, 2022). "Tissue fixation with zinc solution is recommended for the investigation of CD4+ and CD8+ cells markers, but histopathological examination of tissues fixed with zinc solution is laborious and difficult to delineate the different stages of granuloma." (PMID 34604367, 2021). "Immunohistochemical staining of CD4 demonstrated an increase in the number of stained cells in the BCG vaccinated calves compared to non-vaccinated calves in different stages of granuloma." (PMID 34604367, 2021). "Interestingly, the absolute number (i.e., based on total number of cells estimated from the granuloma) of CD4 and CD8 T cells within granulomas from Mtb/SIV NHP was significantly greater than both latent control and Mtb/αCD4 animals." (PMID 32730321, 2020). "In non-human primates, CD153+ Mtb-specific CD4+ T cells are enriched in the airways, and their abundance in individual granulomas correlates inversely with the mycobacterial load." (PMID 32793199, 2020). "Having selectively used CD4+ T-cell responders to PPD in this study, we intuitively expected that T cells would be mainly responsible of the late wave of TNF-α observed following granuloma formation." (PMID 32069329, 2020). "Granuloma formation is promoted by a close relationship between activated macrophages that strongly express major histocompatibility complex (MHC) class II molecules and CD4+ T helper cells 1 (Th1)." (PMID 33628743, 2020). "In 2 of the 5 Mtb/αCD4 NHP with reactivation, new granulomas that appeared during CD4 depletion had no viable Mtb growth (sterile)." (PMID 32730321, 2020). "L-GSH + PZA treatment resulted in a further increase in the expression of CD4 in the granulomas from BCG-vaccinated subjects compared to the non-vaccinated group." (PMID 31569759, 2019). "The reduction of CD4+ and CD8+ T cells and IFN-γ production within granulomas may directly lead to increased M. tuberculosis abundance because of their well-established role in killing M. tuberculosis." (PMID 27462092, 2016). "Whole-slide imaging of hematoxylin and eosin, acid-fast bacilli (AFB), and chromogenic staining for HIV p24, CD3, CD4, CD8, CD15, CD68, interferon γ (IFN-γ), IFN-α, TNF, and IL-10 were used to visualize phenotypic differences within all granulomas and the entire LN section." (PMID 27462092, 2016). "Due to the low numbers of T cells in individual granulomas, which can be quite small in size, individual CD4+ and CD8+ T cell cytokine responses were not analyzed." (PMID 25611466, 2015).
Granuloma (continued). "In contrast, granulomas were observed in liver tissue of mice reconstituted with the colitogenic subpopulation of CD4+CD45RBhi T cells even in the absence of MAP infection." (PMID 24728142, 2014). "Surprisingly, liver granulomas were found in 1 of 4 MAP infected mice reconstituted with CD4+CD45RBlo/int T lymphocytes but not in their uninfected counterparts." (PMID 24728142, 2014). "In conclusion, our results suggest that the presence of noncaseating granulomas on skin biopsy along with BAL lymphocytosis, a high CD4/CD8 ratio, and an elevated serum ACE level are associated with progressive disease." (PMID 23521826, 2013). "However, cytokine production by lymph node cells in antigen restimulation assays indicated increased pan-specific cytokine expression by post-septic CD4+ T cell recipient mice in both TH1 and TH2 granuloma models." (PMID 21655295, 2011). "Based on these studies, it was hypothesized that post-septic CD4+ T cells would show reduced TH1 effector function and increased TH2 effector function in the corresponding granuloma models." (PMID 21655295, 2011). "The development of granulomas is dependent on CD4+ T cells; athymic nude mice do not develop disease and CD4+ T cells from sensitized mice can adoptively transfer disease to naïve recipients." (PMID 21699708, 2011). "Still, the CD4-depleted group (median: 4.5) and CD8α-depleted group (median: 3) had significantly higher numbers of granulomas than the nondepleted vaccinated controls (median: 0), and a small number of clearly unprotected animals in each group had extensive disease (e.g., TB pneumonia)." (PMID 39912921, 2025). "Therefore, changes in the count of peripheral blood CD4+ T lymphocytes are positively correlated with the integrity of tuberculous granulomas, indicating that the infection status of HIV is consistent with the completeness of granuloma formation." (PMID 39205309, 2024). "Analysis of T cells from co-infected patients demonstrated that granuloma formation in leprosy might occur independent of the impaired CD4 T cell response of the HIV infection." (PMID 32849508, 2020). "We were able to identify by PET CT the new granulomas that emerged during CD4 depletion and harvest them at necropsy; surprisingly, no viable Mtb could be recovered from a subset of these." (PMID 32730321, 2020). "However, in MAP infected animals reconstituted with CD4+CD45RBhi T cells more and significantly larger granulomas were found in all 4 mice compared to mice that received CD4+CD45RBhi T cell reconstitution but no MAP infection." (PMID 24728142, 2014). "IL-22 has been suggested to play a protective role in the disease by inhibiting CD4+ T cell migration and collagen deposition and the decrease in IL-22 in the TLR2/9-/- mice may explain the development of granulomas despite decreased T cell activation and TNFα production in these mice." (PMID 24023674, 2013). "Indeed, HP is a chronic disease caused by inhaled agents and is characterized by strong CD4+ T lymphocyte accumulation in the BALF and noncaseating granulomas in the lung tissues." (PMID 21858070, 2011). "Combined with the equivalent CD4+ T cell composition of sham and CLP RAG lymph nodes in both the PPD and SEA models, the modulation in granuloma size does not appear to be due specifically to modulations in CD4+ T cell chemotaxis to the lungs or local draining lymph nodes." (PMID 21655295, 2011). "CD4+CD25+ cells suppressed antigen-specific Th2 mLN cell proliferation in vitro, while their removal during chronic disease resulted in significantly larger granulomas, partial reversal of Th2 hypo-responsiveness and an increase in the number of eosinophils in colonic granulomas." (PMID 21858239, 2011). "We observed similar frequencies of CD4+:CD11c-EYFP+ cell contact between three- and ten-week granulomas, and importantly, found that the statistically significant majority of CD4+ T cells from both three- and ten-week granulomas were in contact with CD11c+ cells." (PMID 20625513, 2010).
Granuloma (continued). "Similarly, CD8+T lymphocytes produce IFN-γ and have an important role in inducing apoptosis of infected cells and both CD4+ and CD8+T lymphocytes can produce pro and anti-inflammatory cytokines that play critical roles in macrophage activation and cell migration involved in formation of granulomas." (PMID 38816607, 2024). "The αCD4 cohort had significantly higher bacterial burden than the IgG group, so it is possible that some aspects of the increased pro-inflammatory milieu in αCD4 granulomas may have been a consequence of increased CFU rather than a direct effect of CD4+ T cell depletion." (PMID 39214090, 2024). "In addition, TB granulomas can actually acquire lymphoid functions: in the absence of secondary lymph nodes, these structures can replace this site for the priming of CD4+ and CD8+ T lymphocytes, as well as functioning as germinal centres of B lymphocytes, providing protective immunity against TB." (PMID 37110276, 2023). "Therefore, the increases in IL-17 production mediated by the CLP CD4+ T cells could play a role in the increased size of the SEA-bead granulomas independent of increased TH2 cytokine production." (PMID 21655295, 2011). "Unlike the mouse model, where the distribution of CD4+ and CD8+ T cells is discrete, these T cells are situated at the periphery in guinea pig granulomas." (PMID 40406522, 2025). "CD4+ T cell depletion in macaques also reduced the number of CD4+ T cells, but not CD8+ T cells or B cells, in tissues, including granulomas and lymph nodes, as compared with macaques that received IgG." (PMID 39214090, 2024). "We compared the cytokine response (Th1, Th17, IL-10) and proliferation (Ki67) of CD4+ and CD8+ T cells to Mtb-specific antigens in lymph nodes without granulomas, with <50% granuloma involvement, and with >50% involvement." (PMID 32790739, 2020). "The proportion of monocytes and CD4+ and CD8+ T lymphocytes determined using flow cytometry was similar between controls and infected patients regardless of their capacity to form granulomas or not (data not shown)." (PMID 32411623, 2020). "The compiled graph comparing the sham treated versus L-GSH treated granulomas from non-vaccinated and BCG-vaccinated subjects demonstrated a significant increase in the mean fluorescent intensity of CD4 in BCG-vaccinated subjects with the addition of L-GSH." (PMID 31569759, 2019). "Control granulomas induced by mBSA-coated beads were composed quite equally of CD8+ and CD4+ T-cells and did not alter antibody titers against Mtb." (PMID 28713389, 2017). "Anti-PD1/PD-1 inhibitors demonstrate a lobular inflammation with CD4+/CD8+ T cells, while anti-CTL4 inhibitors may have central vein endotheliosis and non-necrotizing granulomas." (PMID 33494227, 2021). "The infiltration of CD4- and CD8-positive T cells and the CD4/CD8 ratio seems to not differ between apical granulomas and radicular cysts according to some studies, whereas others describe an increased CD8 infiltration in radicular cysts compared to apical granulomas." (PMID 33540711, 2021).
colon carcinoma (245 papers, 2005 to 2026). "Univariate Cox regression analysis identified that infiltration by neutrophils, conventional dendritic cells (cDC), CD4 + memory T cells, mast cells, and T follicular helper cells was associated with a better prognosis in colon cancer." (PMID 39267963, 2024). "Previous studies have shown that an increased presence of plasma cells, dendritic cells, mast cells, and activated memory CD4 + T cells, along with a decreased presence of M0, M1, and M2 macrophages, is linked to a poor prognosis in colon cancer." (PMID 39267963, 2024). "Clostridium species were reported to promote the accumulation of CD4+ T regulatory cells (Tregs) in colonic mucosa and were associated with Treg cell accumulation in colon cancer (CRC)." (PMID 37894458, 2023). "CD4 + T cells, naive CD4 + T cells, B memory cells, and NK cells were all positively linked with age in colon cancer tissue samples (TCGA-COAD)." (PMID 36633318, 2022). "Results of immune cell infiltration in colon cancer samples showed significant differences in plasma cells, T cells CD4 memory resting, and macrophages M1 between the high-risk and low-risk groups." (PMID 36589748, 2022). "Meanwhile, a large infiltration of activated CD8+ and CD4+ T cells is linked to favorable survival outcome in patients with colon cancer." (PMID 35711437, 2022). "The results showed that CXCL1 overexpression in colon cancer cells increased the infiltration of tumor-associated macrophages (TAMs), while decreasing the CD4 and CD8 cells around the tumor." (PMID 36434686, 2022). "Among patients with colon cancer, a higher proportion of CD4+ T cells was statistically significantly associated with better survival, and the association was weaker for CRC-specific survival than for overall survival." (PMID 34204621, 2021). "In this study, B cell infiltration was found to be a diagnostic predictive feature of colon cancer, and CD4+ T cell infiltration was highly relevant with prognosis of colon cancer." (PMID 32457797, 2020). "In early-stage colon cancer, CD4 memory resting cells may be associated with a better prognosis by contributing to the anti-tumor immune response." (PMID 37465677, 2023). "Among the protective prognostic factors, high levels of ADAD1 have been reported to be strongly associated with the prognosis of colon cancer patients, and its improvement of patient prognosis may be associated with CD4+ T cells." (PMID 36212157, 2022). "Hence, the overexpression of CX3CL1 in tumor cells was shown to inhibit hepatocellular and colon tumor incidence in association with CD4 and CD8 T-cell infiltration in the tumors." (PMID 36429101, 2022). "We witnessed a notable decrease in CD4 T cells in the high-risk group, and we assume that the CD4 function of colon cancer patients might be relatively inhibited or slowed in the high-risk group." (PMID 35154072, 2021). "Moreover, an increase in Th1 CD4+ T-cell expression can reduce the risk of recurrences of colon cancer." (PMID 32104586, 2020). "Additionally, ADAD1 and DLG3, related to CD4+ T cells, were significantly associated with the prognosis of patients with colon cancer." (PMID 32571262, 2020). "Taken together, the preferential differentiation of CD4+ T lymphocyte into the anti-tumor Th1 cells may contribute to the attenuated colon cancer mediated through SHP2 deficiency." (PMID 27935860, 2017). "Additionally, univariate Cox regression analysis showed that infiltration by specific cell types, such as neutrophils, conventional dendritic cells (cDC), CD4 + memory T cells, resting mast cells, and follicular helper T cells, was linked to better prognosis in colon cancer." (PMID 39267963, 2024). "Consistent with the flow cytometry results, the immunofluorescence results revealed that αPD-1 combined with Re-FMT treatment inhibited CD4+ T cell recruitment in colon cancer tissues while promoting CD8+ T cell infiltration." (PMID 40191185, 2025).
colon carcinoma (continued). "In colon cancer, type 2 T helper cells and activated CD4 T cells were highly negatively correlated with RFX1." (PMID 41425715, 2025). "TNFRSF11B is associated with advanced lymph node metastasis and poorer survival outcomes in colon cancer patients, potentially by inhibiting memory-activated CD4+ T cell infiltration." (PMID 40901678, 2025). "IL11 has not been previously associated with AHR but is known to suppress CD4+T cells mediated anti-tumor immunity, and the IL11/STAT3 inhibition increased MHC-I expression and T cell infiltration in colon cancers." (PMID 40283908, 2025). "In this study, we investigated the effect of ULBP2, a ligand for NKG2D, on the efficacy of CD4+CD25+ T cell-targeted immunotherapies using a CT26 mouse colon cancer model engineered to ectopically express ULBP2." (PMID 40558520, 2025). "DIM-3,5 analogs also enhance immune surveillance and reverse CD8+ and CD4+ T cell exhaustion in a syngeneic mouse model of colon cancer." (PMID 40313760, 2025). "De Graaf and colleagues compare neoantigen DNA vaccines for murine colon carcinoma MC-38, containing either tumor-unrelated or tumor-specific CD4+ T cell helper antigens." (PMID 39040850, 2024). "In this study, we used the MHC class II-negative murine colon carcinoma MC-38 to compare tumor-specific and tumor-unrelated CD4+ T cell helper antigens in neoantigen vaccination." (PMID 39040850, 2024). "Meanwhile, PD-L1 on TAMs increased its binding to PD-1 on the surface of effector CD8+ T cells and CD4+ T cells, so it weakened the immune attack of CD8+ T cells and CD4+ T cells, and then mediated immune escape of colon cancer." (PMID 39654892, 2024). "CD4+ T cells are known to play an important role in tumor immunity, which offer a promising strategy for immunotherapy of colon cancer." (PMID 39355236, 2024). "TNFRSF11B is highly expressed in colon cancer and inhibits the infiltration of memory CD4+ T cells in the colon cancer microenvironment, thereby weakening the immune killing response to cancer cells." (PMID 39119088, 2024). "The adjuvant activity of Ad-9D9 was confirmed with a second GAd-based multi-epitope vaccine encoding for 62 CD4 and CD8 neo-antigens selected from the CT26 murine colon carcinoma cell line (GAd-62nag)." (PMID 37180141, 2023). "Lucitanib, a multi-kinase inhibitor, increased CD8+CD4+ T-cell counts and decreased the numbers of DCs and MDSCs in syngeneic mouse colon cancer models." (PMID 37686465, 2023). "Such cells include CXCL13+ CD4+ T cells, which have antitumor effects in colon cancer, CXCL13+ CD8+ T cells, and CXCL13+ CD8+ proliferating T cells." (PMID 37091868, 2023). "Our findings indicated that in the COAD cohort, the Ma2-APOE cluster was associated with a poor prognosis in colon cancer, whereas the cDC1, CD8+Trm, and CD4+Tn clusters were associated with a good prognosis." (PMID 37675100, 2023). "The ‘T cell rich’ TME in our patient cohort shows consensus with previous reports as well as studies where higher ratios of CD4/CD8 T cells have been reported in human colon cancer samples." (PMID 38074634, 2023). "Colon cancer cell-derived exosomes also exert immunosuppressive activity by promoting expansion of the regulatory T cell (T-reg CD4+CD25highFoxp3+) population through miR-208b’s targeting of PDCD4 (programmed cell death factor 4) in CD4+ T cells." (PMID 36831450, 2023). "Rich infiltration of CD8 + tumor-infiltrating lymphocytes, CD4 + T helper cells and activation of type I interferon signaling were associated with the signature of dMMR-MSI colon cancer, which was considered to benefit from immunotherapy." (PMID 36977982, 2023). "TNFRSF11B is a prognostic factor in colon cancer and suppresses memory CD4 + T cell infiltration in the colon cancer microenvironment." (PMID 37543576, 2023).